CXCL9 (C-X-C motif chemokine ligand 9)
Diseases named in the same sentence as CXCL9 in open-access papers (continued):
Sharing a sentence is not in itself a finding about the gene and the disease.
melanoma (continued). "We used the sensitive and reproducible ECIS technology to monitor endothelial monolayer integrity during melanoma cell infiltration in real time, and measured the influence of different soluble CXCL9 concentrations." (PMID 21179030, 2011). "CXCL9 revealed a dose-dependent increase of fluorescence (migrated melanoma cells) in the detection zone." (PMID 21179030, 2011). "The results presented in this study demonstrate that CXCL9 secreted by TuECs triggers different types of directional migration, that is, chemotaxis, fugetaxis and chemokinesis in melanoma cells in a concentration-dependent manner." (PMID 21179030, 2011). "This was also confirmed by the fact that the monolayer breakdown was blunted when the soluble chemokine was neutralised with anti-CXCL9 antibody or when the melanoma cells were pretreated with anti-CXCR3 antibody." (PMID 21179030, 2011). "Stimulation with CXCL9 leads to spontaneous activation and consequently migration of the melanoma cells through an endothelial monolayer." (PMID 21179030, 2011). "Immunostaining experiments revealed that upon CXCL9 stimulation, melanoma transmigration led to the formation of ‘holes’ in the endothelial monolayer and subsequently to the complete EC monolayer disruption." (PMID 21179030, 2011). "CXCL9 increased the EC monolayer disruption during melanoma infiltration in all three primary melanoma cells in a concentration-dependent manner." (PMID 21179030, 2011). "Several studies have shown that CXCL9 is released by cancer cells, including melanoma or renal cancer cell." (PMID 20068563, 2010). "Using mouse melanoma and breast tumor models, we found that PU.1 inhibition by DB suppressed tumor growth, likely through promoting CXCL9 expression in TAMs, which enhances the tumor infiltration of lymphocytes, including CD4+ Th1, CD8+ cytotoxic T lymphocytes (CTLs), and NK cells." (PMID 40867314, 2025). "Although increased STAT3 and NF-κB activity in IκBζ-expressing melanoma could explain the elevated expression of IL-6 and IL-1 cytokines, STAT3 and NF-κB inhibition was unable to recover IκBζ-mediated suppression of Cxcl9, Cxcl10, and Ccl5 in melanoma cells." (PMID 40562773, 2025). "In patients with melanoma, endogenous secretion of CXCL9 and CXCL10 positively correlates with improved prognosis and overall response by induction of CD8+ T-cell recruitment to the tumor site and correlates with improved response to anti–PD-1 and anti–CTLA-4 blockade in vitro." (PMID 39867570, 2025). "Collectively, these results describe that DNMTi-induced ICAM-1 upregulation correlates with a modulation of melanoma secretome in inducing the secretion of the T-cell chemokines CXCL9 and CXCL10 and with the survival positive predictor 12-chemokine melanoma signature." (PMID 39867570, 2025). "In a melanoma mouse model, Batf3+ DCs were a dominant source of CXCL9." (PMID 38928238, 2024). "Collectively, these results demonstrated that NPTyr-C9AP could induce anti-tumor effects in different melanoma models via coexpressing CXCL9 and αPD-L1 to enhance intratumoral infiltration and activation of T cells." (PMID 37031188, 2023). "Collectively, NPTyr-C9AP that locally coexpressed CXCL9 and αPD-L1 in melanoma was more potent in enhancing the intratumoral infiltration and activation of T cells than the systemic injection of anti-PD-L1 antibody, thereby inducing superior antimelanoma effects." (PMID 37031188, 2023). "To explore whether MC1R also represses CXCL9/10/11 transcription in human melanoma, we compared the transcriptomes of MC1R-high versus MC1R-low non-RHC melanoma cases in TCGA." (PMID 37714844, 2023). "We therefore tested whether inhibition of cancer cell-derived Cxcl9/10 expression by MC1R signaling is sufficient to mediate immune evasion of B16F10 melanoma." (PMID 37714844, 2023).
melanoma (continued). "Taken together, these results demonstrated that NPTyr-C9AP could mobilize melanoma cells to coexpress CXCL9 and αPD-L1 to enhance both the recruitment and activation of T cells, thereby resulting in synergistic tumor-killing effects." (PMID 37031188, 2023). "Taken together, high MC1R expression correlates with low CXCL9/10/11 expression independent of tumor mutation burden in human melanoma." (PMID 37714844, 2023). "Thus, T cells were expected to be recruited into melanoma by the CXCL9 gradient between melanoma and peripheral lymphoid organs." (PMID 37031188, 2023). "This study also found that the CXCR3/CXCL9 axis enhances melanoma cell adhesion and may therefore also promote melanoma cell proliferation, survival and apoptosis." (PMID 37170733, 2023). "A Tyr promoter-driven CXCL9 expression plasmid (pTyr-CXCL9), expressing only CXCL9 specifically in melanoma cells, was constructed and encapsulated into NPTyr-CXCL9, which was used as a control for independently evaluating the efficiency of NPTyr-C9AP on T-cell recruitment." (PMID 37031188, 2023). "In the melanoma sample (patient 16), CXCL9, CXCL10, CXCL11, and CXCL13 as well as tumor growth factor beta (TGF-β) were higher at the tumor periphery, indicating that T cells in this region are subject to a unique chemokine and cytokine milieu compared with those deeper within the tumor." (PMID 35584630, 2022). "However, high concentrations of CXCL9 and 10 produced by endothelial cells induced trans-endothelial migration (chemo-repulsion) of melanoma cells, arguing for a dose-dependent effect of the chemokine gradients." (PMID 35626062, 2022). "Thus, the association of PRAME, CXCL9, CXCL10, S100A7, S100A8, and S100A9 with melanoma progression is supported by prior studies and commercially available clinical tests." (PMID 35008167, 2021). "Similarly, we also observed a significantly lower OR effect size for CXCL9 expression in melanoma as compared to urothelial cancer (p = 3.3 × 10−2)." (PMID 33508232, 2021). "CXCL9 is an IFN-γ-inducible chemokine that has been associated with the activation of T helper type 1 immunity in the TME and favorable responses to chemotherapy and immunotherapy in melanoma." (PMID 32635224, 2020). "Recent evidence suggests that CCL4 and CCL5, but not CXCL9-11, are positively associated with survival in melanoma." (PMID 32841222, 2020). "Furthermore, CXCL9 and CXCL10 expression in primary melanoma samples from patients was associated with greater CD8+ T cell infiltration whereas biopsies taken from metastatic lesions were lower." (PMID 30899263, 2019). "Thus, CXCL9/10, a chemokine associated with CD8+ T cell infiltration, was produced by Batf3-driven CD103+ DCs present in the melanoma microenvironment." (PMID 30899263, 2019). "Furthermore, a Genentech-sponsored study of therapeutic anti-PD-L1 antibody showed a significant positive correlation between therapeutic response and baseline CXCL9 levels in melanoma." (PMID 30873179, 2019). "One melanoma study suggested that under IFN-γ stress, melanoma variants which fail to produce CXCL9 could be generated as a mechanism of immune escape." (PMID 30320116, 2018). "Furthermore, in a study on melanoma a 12-chemokine signature that was related to immune infiltrates included high expression of CXCL9, 10, 11, 13, and CCL 3 and 4, similarly to TSCC/BOTSCC in the present study." (PMID 29587383, 2018). "In addition, in vitro stimulation of melanoma cell lines with CXCL9 induced cytoskeletal rearrangements, cell adhesion and migration, that favor cell trafficking and metastasis." (PMID 30420855, 2018). "Interestingly, tumor endothelial cells facilitate melanoma migration through their production of CXCL9 (and CXCL10)." (PMID 30420855, 2018).
melanoma (continued). "In sum, the current study describes a mechanism by which SSeCKS attenuates peritoneal metastasis of experimental melanoma models by controlling the expression and secretion of Cxcl9/10 by specific peritoneal TME cells, PMF, in PKC-, PKA- and PI3K/AKT-dependent manners." (PMID 29050279, 2017). "Moreover, macrophages are a major source of CCL2, CCL3, CCL4, CCL5, CXCL9 and CXCL10, which are important chemokines that induce T lymphocyte chemotaxis, and which we find in association with stromal activation in actual melanomas." (PMID 28448494, 2017). "In melanoma, it has been demonstrated that up regulation of expression of several chemokine genes such as Ccl2, Ccl3, Ccl4, Ccl5, Cxcl9, and Cxcl10 in the tumor microenvironment correlates with the recruitment of activated effector T cells to the tumor increasing antitumor immunity." (PMID 27876058, 2016). "In our in vitro studies reported here we could further demonstrate that soluble CXCL9 promotes the migration of melanoma cells through an EC monolayer in a dose-dependent manner." (PMID 21179030, 2011). "No change in resistance could be detected when monolayers were stimulated with CXCL9 itself or with substances secreted by melanoma cells, contained in the supernatant." (PMID 21179030, 2011). "Taken together, these results indicate that CXCL9 expression in ECs promotes TEM of melanoma cells." (PMID 21179030, 2011). "Furthermore, pretreatment with CXCL9 increases the disruption of endothelial cell–cell contacts when the EC monolayer is brought in close contact with the melanoma cells." (PMID 21179030, 2011). "As a result of our study, one could argue that CXCL9 expressed by tumour stroma cells promotes the escape of the melanoma cells from tumour metastases." (PMID 21179030, 2011). "Penetration of melanoma cells could be significantly decreased when CXCL9 was preincubated with anti-CXCL9 antibody or when the melanoma cells were treated with anti-CXCR3 antibody for 1 h before the challenge of the EC monolayer." (PMID 21179030, 2011). "Finally, ADAR1i-124, like siAdar1, upregulated expression of IFN-stimulated genes (ISGs) such as Ifih1 (MDA5), Cxcl9, and Cxcl10 in Yumm1.7 melanoma and HGS2 ovarian cancer (OC) cells, indicating that ADAR1i-124 activates IFN signaling, a crucial step for effective ICB." (PMID 41608661, 2026). "Thus, the Tyr promoter drove EGFP expression specifically in B16-F10 melanoma cells, although NPTyr-C9AP indiscriminately delivered pTyr-C9AP into different cells, demonstrating the potential melanoma specificity of NPTyr-C9AP for expressing the target genes (CXCL9 and αPD-L1)." (PMID 37031188, 2023). "In addition, ELISA analysis indicated that the CXCL9 protein concentration in melanoma was increased to 14.07 ng g−1 by NPTyr-C9AP treatment, and the serum CXCL9 concentration was correspondingly elevated to 0.26 ng ml−1 due to the diffusion of CXCL9 from the melanoma to the periphery." (PMID 37031188, 2023). "In addition, the numbers of CD69-positive CD8+ T cells in melanoma of NPTyr-αPD-L1, NPTyr-CXCL9 & anti-PD-L1 or NPTyr-C9AP groups respectively reached 3.71, 6.34 or 7.56 × 105 cells per gram tumor, which was 1.3-, 2.2- and 2.6- fold of that in the anti-PD-L1 group." (PMID 37031188, 2023). "In addition, inhibition of CXCL9 expression promotes intracellular actin polymerization, cell adhesion, and cell survival; increases the intracellular calcium concentration; and induces the migration of melanoma cells." (PMID 36479091, 2022). "Both RNAseq and NanoString analyses showed that melanoma tumors grown in Siah2−/− mice exhibit reduced expression of Ccl17 and Ccl22, chemokines expressed by tolerogenic DCs49,50, along with increased expression of Cxcl9, a chemokine functioning in T cell recruitment to tumor sites." (PMID 31911617, 2020). "In addition, high expression of CXCL9 was observed in melanoma-derived cancer stem cells (CSC), which may accelerate efficient recognition and kill by NK cells." (PMID 32974144, 2020).
melanoma (continued). "Specifically, pro-inflammatory CXCL9+CXCL10+ TAMs are enriched in SCC, while tissue-remodelling SPP1+ TAMs are predominant in melanoma." (PMID 41636115, 2026). "The C-X-C motif chemokine ligand genes CXCL9, CXCL10, and CXCL11 were up-regulated in patients with high MOTIscores in gastric cancer and melanoma, and we confirmed this finding for different cancer types in the independent MTB cohort." (PMID 41463470, 2025). "In M160915, GUA induced strong upregulation of the T-cell chemokines CXCL9 and CXCL10, which were previously reported to be expressed in highly T-cell–infiltrated melanoma." (PMID 39867570, 2025). "In melanoma cells, IFN‐γ signalling has been demonstrated to drive antigen presentation and the release of chemokines that recruit T cells (such as CXCL9 and CXCL10)." (PMID 39812592, 2025). "Intratumoural expression of anti-tumoural chemokines such as CXCL9, CXCL10 and CCL5 were reported in patients undergoing chemotherapy for multiple cancer types such as melanoma, non-small cell lung cancer (NSCLC) and BC." (PMID 40852716, 2025). "Concurrently, suppression of IFN-γ response genes (CXCL9, CXCL10, STAT1) mirrors observations in melanoma and lung cancer, where similar transcriptional silencing correlates with T cell exclusion and ICI resistance." (PMID 40873541, 2025). "The correlation between IDO1 and CXCL9 (as an IFN-γ responsive marker) has been assessed in colorectal carcinomas, melanomas, and other cancer types, but the correlation between IDO and IL-10RA in real tumours remains poorly elucidated." (PMID 39592739, 2025). "CD8+ T cells from melanoma tumour mass of LSP1 KO mice exhibited higher migration ability in response to CXCL9 and CXCL10, whereas T cell-specific LSP1 overexpression in transgenic mice resulted in suppressed immune infiltration and promoted melanoma growth." (PMID 40038352, 2025). "Using Pf4 Cx3cr1 mice to deplete CD206hi IMs expressing Cxcl13, Cxcl9, and Cxcl10, we demonstrate their essential role in TLS formation, lymphocyte recruitment, and tumor suppression in melanoma and lung adenocarcinoma." (PMID 40630529, 2025). "Recent studies on anti-PD1 monotherapy have demonstrated that CXCL9 and CXCL10 were crucial, since its receptor CXCR3 was found to be the arbitrator for the PD-1+ CD8+ T cells infiltration in B16 murine melanoma tumours." (PMID 40852716, 2025). "Based on these findings, we propose that constitutively expressed IκBζ in melanoma recruits HDAC3 and EZH2 to the gene loci of CXCL9, CXCL10, and CCL5, leading to inaccessible promoter regions of these genes." (PMID 40562773, 2025). "In particular, as compared to B16F1 melanoma, AT-3 tumors were enriched in mediators of leukocyte infiltration, including chemokines like RANTES, MCP-1 and − 5, fractalkine, CXCL9, 10 and 16, as well as endothelial adhesion molecules like ICAM-1 and VCAM-1." (PMID 38493157, 2024). "Consistent with this, paracrine Cxcl9 and Cxcl10 was significantly upregulated after the introduction of K510A mutant EZH2 into melanoma cells with endogenous EZH2 silencing." (PMID 38461299, 2024). "The most relevant human cancers in this context are melanoma, non-small cell lung cancer (NSCLC), ovarian cancer, gastric cancer, and colorectal cancer, where high levels of CXCL9/CXCL10 indicate favorable prognosis and low levels poor prognosis." (PMID 39474427, 2024). "Five genes (CXCL10, TNF, PIK3CD, PIK3R2, and CXCL1) of the TNF signalling pathway and seven genes (CXCL9, GDF15, BMP7, TNFRSF15, CXCL10, TNF, and CXCL1) of the cytokine–cytokine receptor pathway were commonly upregulated in melanoma cells." (PMID 39496484, 2024). "In a melanoma mouse model, CD103+ DC-derived CXCL9 was required for an effective CD8+ T cell response and clinical response to anti-PD-1 therapy." (PMID 38928238, 2024). "CXCR3 ligands such as CXCL9 and CXCL10 as indirect markers of T-cell infiltration have been identified in the past as indicating a response to ICI in stage IV melanoma." (PMID 38562921, 2024).
melanoma (continued). "In numerous cancers, among them melanoma, non-small cell lung cancer (NSCLC), ovarian cancer, gastric cancer, and colorectal cancer, high CXCL9/CXCL10 levels indicate favorable prognosis, and low levels indicate poor prognosis." (PMID 39474427, 2024). "QRT‒PCR analysis verified that both CXCL9 and αPD-L1 mRNA were highly expressed in melanoma tissues after intravenously injecting NPTyr-C9AP into mice bearing B16-F10 melanoma." (PMID 37031188, 2023). "Owing to the synergy of CXCL9 and αPD-L1, the number of CD69-positive CD8+ T cells in NPTyr-C9AP-treated melanoma reached 2.33 × 105 cells per gram tumor, which was 5.1- and 2.1-fold that in the NPTyr-CXCL9 and NPTyr-αPD-L1 groups, respectively." (PMID 37031188, 2023). "Taken together, we conclude that MC1R represses the expression of Cxcl9, Cxcl10, and Cxcl11 in B16F10 melanoma." (PMID 37714844, 2023). "Chemokines secretion (CXCR6, CXCL9, CCL5, and CCR5) was also shown to predict response to anti–PD-1–directed therapy in melanoma patients." (PMID 37875556, 2023). "Taking the CXCL9 gene as an example, we found that the expression of the CXCL9 gene was higher when the Clark grades were II, III, and IV in melanoma patients." (PMID 37666853, 2023). "injection of NPTyr-C9AP into mice bearing different melanomas, the intratumoral concentrations of CXCL9 and αPD-L1 were 11.11 and 36.82 ng g−1 in NPTyr-C9AP-treated Clone M-3 melanoma, and were 15.06 and 54.79 ng g−1 in NPTyr-C9AP-treated YUMM1.7 melanoma." (PMID 37031188, 2023). "Of interest, addition of an anti-CXCR3 antibody after ACT in IL-2 NOG mice bearing the Me275 melanoma tumor, known to express CXCR3 ligands i.e. CXCL9/10/1140, with DMβ-transduced T cells significantly impaired tumor control." (PMID 37280206, 2023). "Activation and expression of CXCL9 gene recruits immune-infiltrating cells such as lymphocytes to TME, thereby enhancing melanoma anti-tumor immunity." (PMID 37666853, 2023). "B16-F10 melanoma-bearing mice were intravenously injected with PBS, anti-PD-L1 antibody, NPTyr-αPD-L1, NPTyr-CXCL9 & anti-PD-L1 antibody or NPTyr-C9AP every other day for five injections." (PMID 37031188, 2023). "Our previous cytokine and chemokine profiling in short term cultures of dissociated YUMM3.3 melanoma grafts showed that Activin-A secretion by the cancer cells diminishes both the levels of IFN-γ and the secretion of CXCL9 and CXCL10 in the conditioned medium." (PMID 38304252, 2023). "Accordingly, in comparison with NPTyr-CXCL9 and NPTyr-αPD-L1 groups, the number of CD3+ T cells in NPTyr-C9AP-treated melanoma were significantly increased to 1.87 × 106 cells per gram tumor, verifying the synergistic effect of CXCL9 and αPD-L1." (PMID 37031188, 2023). "In human melanomas, high MC1R expression correlates with reduced CXCL9/10/11 expression, impaired T cell infiltration, and poor patient prognosis." (PMID 37714844, 2023). "The mRNA expression of CXCL9 and αPD-L1 in NPTyr-C9AP-treated melanoma reached 459.5- or 584.1-fold that of the PBS group." (PMID 37031188, 2023). "The major chemokine/chemokine receptor interactions occurring in melanoma development and progression include the CXCR4/CXCR7/CXCL12, CXCR3/CXCL9,10,11, CXCR1,2/CXCL8, CCR2/CCL2, CCR4/CCL17,22, CCR5/CCL5, CCR7/CCL21 and CCR10/CCL27 axes." (PMID 37170733, 2023). "CXCL9 and CCL5 activated immune responses and enhanced ICB therapy in mouse model of ovary cancer, and the melanoma in CXCR3 knock-out mice exhibited decreased immune infiltration and poor prognosis." (PMID 35692828, 2022). "In breast cancer and melanoma, we demonstrated that HIF-dependent expression of BIRC2 led to decreased CXCL9 expression, which prevented the recruitment of CD8+ T cells and NK cells to the tumor." (PMID 35499076, 2022). "The CXCR3 ligands CXCL9 and CXCL10 also have been successfully delivered via viral-vectors in colon and melanoma mouse models." (PMID 35626062, 2022).